IL1B (interleukin 1 beta)
Diseases named in the same sentence as IL1B in open-access papers (continued):
Sharing a sentence is not in itself a finding about the gene and the disease.
endothelial dysfunction (continued). "The presence of inflammation was also supported by the increased expression in the myocardium of mRNA coding for Il1b and for Vcam1, an adhesion molecule responsible for the adhesion of leukocytes to the endothelium, suggesting endothelial dysfunction." (PMID 31393963, 2019). "It was also found that Alu up-regulated the expression level of IL-1β within the endothelial dysfunction process." (PMID 32038328, 2019). "Decreased circulating EPCs and increased inflammatory biomarkers, including IL-1β and TMAO, were independent risk factors of endothelial dysfunction." (PMID 30862856, 2019). "Canonical NALP3 inflammasome activation is a caspase-1 medicated process, resulting in the secretion of IL-18 and IL-1β which lead to endothelial dysfunction." (PMID 30186184, 2018). "The NALP3 inflammasome, a sensor for metabolic danger, takes part in innate immune response and is critical for the regulation of the inflammatory cytokine IL-1β, which can lead to endothelial dysfunction." (PMID 30186184, 2018). "To this aim, we induced endothelial dysfunction (ED) by activating HUVECs with TNF-α or IL-1β and measured the impact of RES in these cells." (PMID 28610607, 2017). "During the last decade, the proinflammatory cytokines TNF-α and IL-1β have emerged as biomarkers and mediators of oxidative stress and endothelial dysfunction in several cardiovascular diseases." (PMID 27894297, 2016). "Whereas, blocking IL-1β improved endothelial dysfunction in diabetic models and prevented choroidal neovascularization in models of laser-induced retinal degeneration." (PMID 28119571, 2016). "We decided to study the effect of several cytokines involved in the inflammatory process, such as TNF-α, IL-6 and IL-1β on some markers of endothelial dysfunction and activation in ECs and the possible protective effect of the oleate against those stimuli." (PMID 26055507, 2015). "Endothelial dysfunction produced by IL-1β has been previously reported in isolated rat mesenteric microvessels using both short (30 min) and longer (14 h) incubation times with the cytokine." (PMID 25518980, 2014). "Specifically, tat-induced endothelial dysfunction is instigated by dysregulation of ROS production and upregulation of interleukin-1 beta (IL-1β), MCP-1, vascular cell adhesion protein-1 (VCAM-1) and E-selectin expression through activation of the NF-κB signaling pathway, as demonstrated on HUVECs." (PMID 41465377, 2025). "Similarly, an increase in plasma IL-1β and sVCAM-1 was observed in both forms of preeclampsia, suggesting inflammation and endothelial dysfunction, respectively." (PMID 40746439, 2025). "Additionally, IL-1β promote the formation of NETs, aggravating inflammatory responses and endothelial dysfunction." (PMID 40520933, 2025). "M1 macrophages, induced by stimuli such as interferon-gamma (IFN-γ) and lipopolysaccharide (LPS), secrete pro-inflammatory cytokines (TNF-α, IL-1β, IL-6) and reactive oxygen species (ROS), thereby amplifying vascular inflammation and contributing to endothelial dysfunction and plaque instability." (PMID 40871049, 2025). "Moreover, previous studies have demonstrated that Notch1 enhances IL-1β expression and elevates endothelial permeability, thereby precipitating endothelial dysfunction in human brain microvascular endothelial cells." (PMID 40290868, 2025). "Tumour necrosis factor-alpha (TNF-α) and interleukin-1 beta (IL-1β) have been shown to play integral parts in systemic inflammation and endothelial dysfunction, while interleukin-6 (IL-6) and interleukin-8 (IL-8) have been demonstrated to contribute to vascular resistance and thrombosis." (PMID 41439053, 2025). "Interestingly, we found that transfection of these tsRNAs/rsRNAs led to significantly increased expression of several proatherogenic or endothelial dysfunction–related genes including Endothelin (End1), E-selectin (Sele), and Il1b." (PMID 39253968, 2024).
endothelial dysfunction (continued). "In vessels, exposure to IL-1β exerts pro-oxidative actions leading to endothelial dysfunction." (PMID 36536168, 2024). "This activation leads to the rapid release of cytokines such as tumor necrosis factor-alpha (TNF-α), interleukin-1 beta (IL-1β), interleukin-6 (IL-6), and interleukin-18 (IL-18), driving systemic inflammation and leading to endothelial dysfunction, tissue damage, and increased vascular permeability." (PMID 39594987, 2024). "Adalimumab, anti-IL-1β, and FAK inhibitors effectively blocked TNF-α, IL-1β, and reduced FAK activity; improved endothelial dysfunction caused by CAR-T cells, malignant cells, and myeloid cells in CAR-T cells treatment; and reduced endothelial leakage caused by CAR-T and other cells." (PMID 38329486, 2024). "This study examines how glypican-1 shedding, matrix metallopeptidase 9 (MMP9), and the pro-inflammatory cytokine IL-1β may contribute to endothelial dysfunction in patients undergoing on-pump surgery with an extended CPB." (PMID 39857617, 2024). "Endothelial dysfunction may contribute to the accumulation of leukocytes and the induction of tissue damage, as well as the further release of cytokines (IL-6, IL-1B, and TNF-alpha)." (PMID 39598310, 2024). "The PVAT in lupus mice exhibited increased infiltration of immune cells and expression of pro-inflammatory cytokines (e.g., IL-1β, IL-6, TNFα, IFNγ), along with decreased expression of adiponectin, which likely promotes endothelial dysfunction and vascular wall remodeling." (PMID 37006244, 2023). "Furthermore, the activation of this transcription factor also prevents IL-1β-induced VSMC migration and proliferation, as well as the IL-1β-induced endothelial dysfunction." (PMID 36937865, 2023). "Globally, these results point at NLRP3 inflammasome as a main mediator of endothelial dysfunction and premature vascular aging in those pathological conditions in which excess IL-1β may impact the vasculature." (PMID 35111374, 2022). "Besides, the in vivo infusion of IL-1β to mice results in enhanced vascular NLRP3 expression, endothelial dysfunction, and a loss of vasodilatory capacity, which can also be prevented by MCC950." (PMID 35204152, 2022). "These inhibitory effects of DOX on the TLR4/LPS-signaling pathway, including the reduction of the pro-inflammatory cytokines IL-1β and IL-6, could explain the improvement of endothelial dysfunction and diminishing of blood pressure." (PMID 34578849, 2021). "In mouse models, increased IL-17 was associated with reactive oxygen species formation, circulating inflammatory leukocytes and endothelial dysfunction, while higher levels of resistin, TNF-α, IL-1β, and MMP-9 expression were associated with the levels of inflammatory infiltrates in artery walls." (PMID 33868242, 2021). "The pharmacological effects of TNFα/IL1β neutralizing antibodies as well as FAK inhibitor on CAR-T therapy-induced endothelial dysfunction still need to be verified in vivo, and the optimization of the interfering strategies might also be needed." (PMID 34093519, 2021). "Other crucial proinflammatory cytokines such as TNF-α and IL-1β may stimulate leukocyte adherence and migration, which may worsen endothelial dysfunction." (PMID 32410856, 2020). "Since the NLRP3 inflammasome activation yields IL-1β 14,23 we analysed whether the blockade of IL-1 receptors could interfere with visfatin/eNampt-induced endothelial dysfunction." (PMID 32214150, 2020). "Interestingly, the IL-receptor antagonist anakinra prevented the defective relaxation evoked by the in vivo infusion, confirming IL-1β as a key mediator of endothelial dysfunction induced by visfatin/eNampt." (PMID 32214150, 2020). "Endothelial inflammation via TNF-α, IL-1β, or IL-6 pro-inflammatory cytokines favors leukocyte recruitment, endothelial dysfunction and activation of blood coagulation making interleukin-driven proatherothrombotic processes a potential pharmacological target explored in several clinical trials." (PMID 32019950, 2020).
endothelial dysfunction (continued). "As a pro-oxidant, uric acid can decrease the production and bioavailability of nitric oxide, activate NACHT, LRR and PYD domains-containing protein 3 inflammasome, and produce interleukin (IL)-1β, leading to activation of the renin−angiotensin system and endothelial dysfunction." (PMID 31766442, 2019). "Cytokines, including TGF-β1, TNFα, IFNγ, IL-1β, and IL-17A, may regulate blood pressure through effects on endothelial dysfunction, salt and water balance, and sympathetic regulation." (PMID 31572188, 2019). "IL-1β, a common pro-inflammatory cytokine, can lead to endothelial dysfunction." (PMID 30186184, 2018). "Following activation of the NALP3 inflammasome, procaspase-1 is self-cleaved to become active caspase-1 and further turn pro-IL-1β to IL-1β, which may lead to endothelial dysfunction." (PMID 30186184, 2018). "IL-32 also is up-regulated in KCs by IL-1β; this cytokine may induce vascular inflammation and endothelial dysfunction." (PMID 28323859, 2017). "We hypothesized that the high levels of IL-1β and IL-8 secreted by infected macrophages will trigger endothelial dysfunction." (PMID 27582738, 2016). "Moreover, in rat mesenteric microvessels high glucose incubation enhanced the endothelial dysfunction induced by IL1β by a mechanism which was abrogated by the inhibition of the PPP." (PMID 27245224, 2016). "In addition, IL-1β has been considered to be a potential mediator of maternal endothelial dysfunction in PE." (PMID 25222025, 2014). "Endothelial alteration by IL-1β was requiring the activation of IL-1 receptors, since the pre-incubation of the vascular segments with the recombinant human antagonist of IL-1 receptors anakinra led to a concentration-dependent recovery of the endothelial dysfunction evoked by IL-1β." (PMID 25518980, 2014). "The hypertensive phenotype may also contribute to the stimulated IL-1β signal in SHRSP, because hypertension causes endothelial dysfunction and induces vascular inflammation." (PMID 23326018, 2012). "In addition, the inflammation in RA upregulates cytokines, such as tumor necrosis factor-alpha (TNF-α) and interleukin 1 beta (IL-1β), in affected joints that can impact distant sites, create oxidative stress, endothelial dysfunction, plaque instability, and thrombosis." (PMID 38340224, 2024). "Finally, the effect of Nrf2 activation on IL-1β-induced endothelial dysfunction was also analysed." (PMID 36937865, 2023). "Endothelial dysfunction, oxidative stress, VSMCs macrophage foam cells accumulation, toll-like receptor signaling, NLPR-3 inflammasome formation, and subsequent pro-inflammatory cytokine production, such as TNF-α, IL-1β, IL-6 are few of the mechanisms implicated in the atherogenic process." (PMID 35805095, 2022). "Although the exact pathophysiology underlying CNS lesion formation in FMF remains unclear, the increased activity of IL-1β has been suggested to facilitate a proinflammatory milieu that triggers endothelial dysfunction and favors the development of autoreactive lymphocytes." (PMID 34731365, 2022). "One separate study demonstrated that IL-1β may function in the development of diabetic retinal glial cell activation and endothelial dysfunction, thus interrupting the vicious cycle triggered by IL-1β auto-stimulation, which may be a mechanism for limiting the progression of DR." (PMID 35814228, 2022). "TMAO hinders mitochondrial function and energy metabolism by reducing the pyruvate and fatty acid oxidation and activates the release of IL-1β and IL-18 in endothelial cells, thereby promoting endothelial dysfunction which could in turn degrade the intestinal epithelial barrier." (PMID 36287917, 2022). "Similarly, HT-3S can attenuate the morphological changes induced by the inflammatory stimuli IL-1β in endothelial cells, suggesting that HT-3S might have a role in the prevention of endothelial dysfunction and related pathologies." (PMID 34946563, 2021).
endothelial dysfunction (continued). "Given that arginase can regulate NO production in endothelial cells by competing with eNOS for the substrate L-arginine, it is plausible that IL-1β may contribute to endothelial dysfunction by limiting arginine availability for eNOS via increases in arginase activity." (PMID 31412063, 2019). "Because endothelial cells express CB1/CB2 receptors and CBs elicit anti-inflammatory defense facing cytokine-dependent endothelial dysfunction, we examined whether CBs could ameliorate the increase in Cx43 hemichannel activity evoked by IL-1β/TNF-α and high glucose in EAhy cells." (PMID 30158937, 2018). "Furthermore, using rat mesenteric microvessels, we investigated whether how endothelial dysfunction induced by IL1β is potentiated by high glucose concentrations." (PMID 27245224, 2016). "Endpoints assessed included mean changes in plasma inflammatory markers (IL-1β, IL-6, and TNF-α) and endothelial dysfunction markers (syndecan-1), handgrip strength, fatigue scale, and quality of life (QoL)." (PMID 41753154, 2026). "Cytokines such as interleukin-1β (IL-1β) and interleukin-6 (IL-6) further stimulate hepatic production of acute-phase proteins such as C-reactive protein (CRP), contributing to endothelial dysfunction in systemic blood vessels." (PMID 41444986, 2025). "Inflammatory cytokines like IL-1β, IL-6, and TNF-α are elevated following SAH, driving endothelial dysfunction and blood-brain barrier breakdown, which can worsen brain injury." (PMID 40783564, 2025). "Produced by immune, renal, and endothelial cells; drives IL-1β/IL-6 via NF-κB and MAPK; ↑ endothelial dysfunction and proteinuria." (PMID 41154568, 2025). "Mechanically, IR-related markers could increase endothelial dysfunction by activating NF-κB or PI3K/Akt signaling pathways, increasing reactive oxygen species (ROS) production, and secreting proinflammatory cytokines (TNF-α, IL-6, IL-1β), to further improve cardiovascular disease risk." (PMID 41450551, 2025). "Elevated serum uric acid can directly induce endothelial dysfunction and stimulate the production of pro-inflammatory cytokines such as TNF-α and IL-1β." (PMID 41441018, 2025). "First, spontaneous hypertensive rat models show reduced NO levels, elevated ET-1, inflammatory markers (e.g., IL-1β, TNF-α, MCP-1, VCAM-1), and ROS, indicating endothelial dysfunction, inflammation, and oxidative stress." (PMID 40230380, 2025). "Some authors reported that elevated levels of IL-1β, IL-6, and TNF-α not only function as immune effectors but also contribute to endothelial dysfunction, increased vascular permeability, and metabolic disturbances when produced excessively." (PMID 40806937, 2025). "The cytokine pattern observed in our oocyte-donation cohort—with increased IL-6, IL-1β, TNF-α, CXCL10, and VEGF—parallels these findings and supports the concept that immune activation and endothelial dysfunction are central to the disease process." (PMID 41561632, 2025). "It is therefore not surprising that ADMA has been associated with endothelial dysfunction among multiple organ systems, cardiovascular and noncardiovascular, as its presence is associated with increased levels of inflammatory cytokines, including IL-1β, TNF-α, IL-6, IL-10, IL-4, IL-2, and more." (PMID 39941130, 2025). "The infection induces a strong inflammatory response, including a cytokine storm (e.g., IL-6, IL-1β, TNF-α), endothelial dysfunction, and microvascular thrombosis, which exacerbate myocardial injury." (PMID 39771983, 2024). "PA also triggered inflammation and endothelial dysfunction, as evidenced by NLRP3 activation, upregulation of ICAM-1 (endothelial activation marker), and pyroptotic markers (NLRP3, GSDM-D, IL-1β, IL-18)." (PMID 39770410, 2024).
endothelial dysfunction (continued). "Our study demonstrated that PA-induced endothelial dysfunction significantly increased expressions of NLRP3, ICAM-1, GSDM-D, and pro-inflammatory cytokines IL-1β and IL-18 in the HUVECs during PA-induced pyroptosis." (PMID 39770410, 2024). "Specifically, the uncontrolled release of pro-inflammatory cytokines such as IL-1β, IL-6, and TNF-α leads to myocardial depression, endothelial dysfunction, and triggers apoptosis pathways in cardiac cells." (PMID 38326366, 2024). "In step-flow chamber, d-flow markedly inhibited MerTK expression while induced endothelial dysfunction, indicating increased expression of pro-inflammatory signaling such as NLRP3 inflammasome (NLRP3, pro-IL-1β, and cleaved IL-1β), TNF-α, and NF-κB." (PMID 38646649, 2024). "Endothelial dysfunction plays a large role in AAA formation and progression and is influenced by IL-1β signaling." (PMID 37476160, 2023). "Inhibition of miR-19b-3p reduced TNF-α and IL-1β expression levels in ox-LDL-HUVEC and AS mice and mitigated endothelial dysfunction." (PMID 37469665, 2023). "Systematic inflammation and circulating cyto- and chemokines including C-reactive protein, IL-6, IL1β, and TNFα fuel CVD through endothelial dysfunction, altered vascular tone, enhanced plaque formation, and coagulation." (PMID 36564799, 2022). "Several studies have demonstrated the capability of ASA to attenuate the hepatotoxicity and endothelial dysfunction by regulating the NLRP3 inflammasome and IL-1β levels." (PMID 35335908, 2022). "As a result, a cascade of pro-inflammatory markers including IL-1β, IL-6 and TNF-α were upregulated, eventually leading to endothelial dysfunction, as displayed by EDR impairment." (PMID 40477401, 2021). "In a model of arthritis, endothelial dysfunction was only observed in rats with a persisting imbalance between NOS and COX-2 pathways, higher plasma levels of IL-1β and tumor necrosis factor-α (TNF-α)." (PMID 33868242, 2021). "IL-1β, IL-6, and ICAM-1 are important proinflammatory molecules, which play crucial roles in the preliminary inflammatory response and endothelial dysfunction." (PMID 34221236, 2021). "Uric acid is known to promote inflammation and endothelial dysfunction and its crystals, monosodium urate (MSU) promote the release of IL-1β via activation of the NLRP3 inflammasome." (PMID 32093005, 2020). "For instance, pro-inflammatory metabolites (such as NO-related molecules), cytokines (including IL-1β, TNF-α, IFN-γ, IL-4, IL-5, IL-8, G-CSF, and MIP-1b), and markers of endothelial dysfunction (e.g., homocysteine) were found to be increased in VaD patients." (PMID 32340195, 2020). "Studies have shown that inflammatory factors IL-6, IL-1β, IL-18, and TNF-α are positively correlated with cardiovascular events and are also involved in the occurrence of endothelial dysfunction." (PMID 33014270, 2020). "In order to delineate the pathogenesis of MDS-related endothelial dysfunction suggested by the prognostic impact of EASIX, we measured serum levels of S100A9, IL1β and IL18 (both activated by caspase 1 from pro-cytokines)." (PMID 31712595, 2019). "In our data, the expression of IL-6, IL-1β, and MMP-9 increased in the intestinal tissues of the irradiated group and the result suggested that intestinal inflammation is accompanied by endothelial dysfunction in radiation-induced intestinal injury." (PMID 31474856, 2019). "Not surprisingly, many of the most upregulated genes are well-known markers of endothelial dysfunction (e.g., SELE, ICAM1, SOD2, IL8, IL1B)." (PMID 31287004, 2019). "The molecular targets through which aging perturbs vascular homeostasis are manifold and appear to include increased expression or activation of TNF-α, IL-1β, IL-6 family members and CRP, which promote inflammation and endothelial dysfunction." (PMID 28840062, 2017).